IL9 (interleukin 9)
Diseases named in the same sentence as IL9 in open-access papers (continued):
Sharing a sentence is not in itself a finding about the gene and the disease.
liver fibrosis (continued). "However, it is worth noting that our cytokine profile findings seem to be different from those seen in schistosomiasis mansoni, which has shown higher levels of IL-9, IL-10 and IL-17 in patients with advanced liver fibrosis." (PMID 37887717, 2023). "Importantly, we showed decreased percentages of Th9, Th17 and Th1 cells in spleen along with an attenuation of hepatic fibrosis in IL-9-neutralized mice, indicating endogenous IL-9 plays a deleterious role in hepatic fibrogenesis." (PMID 26728971, 2016). "Our data suggest a deleterious role of Th9/IL-9 in increasing hepatic fibrosis and exacerbating disease endpoints, indicating that Th9/IL9 based immunotherapy may be a promising approach for treating hepatic fibrosis." (PMID 26728971, 2016). "Furthermore, we found that percentages of splenic Th9 and Th17 cells, plasma concentrations and liver expression of both IL-9 and IL-17A were significantly higher in mice with hepatic fibrosis than in controls." (PMID 26728971, 2016). "Altogether, Th9/IL9 has a deleterious role that leads to increased hepatic fibrosis." (PMID 26728971, 2016). "Neutralization of IL-9 in mice ameliorated hepatic fibrosis, attenuated the activation of hepatic stellate cells, reduced frequencies of Th9, Th17 and Th1 cells in spleen, and suppressed expression of IL-9, IL-17A, IFN-γ, TGF-β1, IL-6, IL-4 and TNF-α in plasma and liver respectively." (PMID 26728971, 2016). "The mRNA levels of IL-9 and IL-17A were higher in mice with liver fibrosis than in controls." (PMID 26728971, 2016). "Furthermore, plasma levels of IL-9 and IL-17A were significantly correlated with the percentages of splenic Th9 and Th17 cells in mice with hepatic fibrosis, respectively." (PMID 26728971, 2016). "Furthermore, IL-9 neutralization in mice with hepatic fibrosis significantly reduced Th9 cells in spleen, and suppressed IL-9 expression in plasma and liver, attenuated HSCs activation, and ameliorated hepatic fibrosis, suggesting that Th9/IL-9 axis facilitated HSCs activation in hepatic fibrosis." (PMID 34234100, 2021). "Hence, the results indicate that IL-9 might influence the hepatic fibrosis by promoting the synthesis and accumulation of PC-III, whereas it moderately regulates HA expression during S. japonicum infection." (PMID 28539607, 2017). "Results demonstrated that IL-9 antibody could obviously reduce the level of PC-III in mouse serum (P < 0.05), and suggested that IL-9 could influence hepatic fibrosis by promoting the synthesis and accumulation of PC-III in the course of S. japonicum infection." (PMID 28539607, 2017). "Th9/IL-9 may serve as a potential target for therapeutic intervention of hepatic fibrosis." (PMID 26728971, 2016). "Furthermore, we showed that anti-IL-9Ab treatment decreased numbers of Th subsets including Th9, Th17 and Th1, indicating that IL-9 may down-regulate the proliferation of Th9, Th17 and Th1 cells in response to hepatic fibrosis." (PMID 26728971, 2016). "Higher levels of IL-9, IL-10, and IL-17 were found in PBMC supernatants of patients with advanced hepatic fibrosis." (PMID 34970264, 2021). "However, the role of Th9/IL-9 cells in hepatic fibrosis is unknown." (PMID 26728971, 2016). "In this study, we observed significantly increased percentages of Th9 and levels of IL-9 in plasma of CHB and LC patients with liver fibrosis compared with HC." (PMID 26728971, 2016). "The elevated serum concentrations of IL-9, IL-17 and fibrogenic basic fibroblast growth factor in plasma of HBV mono-infected patients support recent reports highlighting the roles of these biomarkers in pathogenesis of liver fibrosis due to viral hepatitis." (PMID 29739341, 2018). "We further examined the role of the endogenous IL-9 in hepatic fibrosis and its relationship with other relevant cytokines, including IL-17A, IFN-γ, TGF-β1, IL-6, IL-4, IL-21 and TNF-α in response to hepatic fibrosis, by neutralizing IL-9 in a mouse model." (PMID 26728971, 2016).
liver fibrosis (continued). "Neutralization of IL-9 further suppressed expression of inflammatory cytokines including IL-9, IL-17A, IFN-γ, TGF-β1, IL-6, IL-4 and TNF-α in the mouse model of hepatic fibrosis, suggesting IL-9 may regulate the inflammatory responses to liver fibrosis." (PMID 26728971, 2016).
Sepsis (12 papers, 2018 to 2026). Sepsis is defined as life-threatening organ dysfunction caused by a dysregulated host response to infection. "Our recent research also determined that the proportions of Th9 cells, as well as the expression levels of IL-9, were particularly associated with acute intestinal barrier dysfunction in sepsis." (PMID 35042191, 2022). "Secondly, the animal experiments in this study, by constructing a sepsis model and imposing different treatments, analyzed the effect of changes in IL-9 on ferroptosis in sepsis." (PMID 41085701, 2026). "We greatly appreciate and recognize the study’s conclusion that increased expression of IL-9 promotes ferroptosis to further induce sepsis." (PMID 41085701, 2026). "The serum concentrations of αEβ7, IL-9, and D-lactate were reduced in the control cohort in contrast with the sepsis cohort and the sepsis+αEβ7e cohort (P <0.001)." (PMID 35042191, 2022). "Our study found that the E-cadherin levels in both serum and intestinal tissue were reduced progressively in the control group, sepsis+αEβ7i cohort, sepsis cohort, and sepsis+αEβ7e cohort, whereas the IL-9 or αEβ7 were opposite." (PMID 35042191, 2022). "The Th9 cell proportions, αEβ7, IL-9, and D-lactate levels in both serum and intestinal tissue of the sepsis cohort were higher in contrast with those of the control cohort." (PMID 35042191, 2022). "The results of western blot revealed that the levels of αEβ7, IL-9, and D-lactate expression in the intestine were relatively low in the control cohort in contrast with the those in the sepsis cohort (P <0.01) or the sepsis+αEβ7e cohort (P <0.001)." (PMID 35042191, 2022). "The Th9 cells percentages, αEβ7, IL-9, and D-lactate levels of the sepsis cohort were significantly higher than those of the control cohort." (PMID 35042191, 2022). "The penetration depth of tracer was gradually increased in the control group, sepsis+sh-IL-9 group, sepsis group, and sepsis+IL-9 group (P < 0.05)." (PMID 33941281, 2021). "The percentage of apoptotic cells in intestinal mucosa was gradually increased in the control group, sepsis+sh-IL-9 group, sepsis group, and sepsis+IL-9 group (P < 0.01)." (PMID 33941281, 2021). "Survival rate analysis also showed that the survival rate of rats was gradually decreased in the control group (100%), the sepsis+sh-IL-9 group (70%), the sepsis group (50%), and the sepsis+IL-9 group (20%) (P < 0.001)." (PMID 33941281, 2021). "Compared with the sepsis group, the expression levels of IL-9 and D-lactate were significantly increased in the sepsis+IL-9 group (P < 0.01), whereas those were significantly decreased in the sepsis+sh-IL-9 group (P < 0.001)." (PMID 33941281, 2021). "A total of 48 SD rats were randomly assigned to four groups as follows: control group, sepsis group, sepsis+sh-IL-9 group, and sepsis+IL-9 group." (PMID 33941281, 2021). "This study firstly proved that IL-9-producing CD4(+) T cells and IL-9 were also closely related to the barrier injury and mortality in sepsis." (PMID 33941281, 2021). "Overall, our results demonstrated that IL-9 is involved in the damage of the intestinal mucosal barrier in sepsis." (PMID 33941281, 2021). "Previous reports also showed that group 2 innate lymphoid cell-derived IL-9 reduces mouse lung endothelial cell (MLEC) pyroptosis in sepsis through attenuating caspase-1 activation in MLECs." (PMID 34992715, 2021). "To functionally confirm the role of IL-9-producing CD4(+) T cells and IL-9 in the intestinal pathology, we used a rat sepsis model." (PMID 33941281, 2021). "The sepsis-induced intestinal mucosal injuries were significantly improved or aggravated by IL-9 interference or IL-9 overexpression, respectively." (PMID 33941281, 2021). "This study suggested that IL-9 is closely related to the intestinal mucosal barrier injury in sepsis." (PMID 33941281, 2021).
Sepsis (continued). "The serum percentages of IL-9-producing CD4(+) T cells of the control group were significantly lower than that of the sepsis group (0.43%±0.03% vs. 1.58%±0.41%, P =0.021) or the sepsis+IL-9 group (0.43%±0.03% vs. 3.53%±0.90%, P < 0.001)." (PMID 33941281, 2021). "The IOD values of fluorescent tracer were gradually increased in the control group, sepsis+sh-IL-9 group, sepsis group, and sepsis+IL-9 group (P < 0.01)." (PMID 33941281, 2021). "The specific mechanism by which IL-9-producing CD4(+) T cells are involved in the mucosal barrier injury of sepsis needs further research." (PMID 33941281, 2021). "Western blot analysis showed that the expression levels of IL-9 and D-lactate in intestinal tissue of controls were significantly lower than that of the sepsis group (P < 0.05) and the sepsis+IL-9 group (P < 0.001)." (PMID 33941281, 2021). "Survival rate analysis of animal models also showed that IL-9 decreased the 14-day survival rate of sepsis rats." (PMID 33941281, 2021). "The percentages of tissue IL-9-producing CD4(+) T cells in the control group were significantly lower than that in the sepsis group (0.22%±0.04% vs. 1.02%±0.07%, P < 0.001) or the sepsis+IL-9 group (0.22%±0.04% vs. 1.57%±0.10%, P < 0.001)." (PMID 33941281, 2021). "In the present study, we found that IL-9 mainly played a pro-inflammatory role in the intestinal mucosal injury of sepsis." (PMID 33941281, 2021). "The serum IL-9 and D-lactate levels in the control group were significantly lower than that of the sepsis group and sepsis+IL-9 group (P < 0.01)." (PMID 33941281, 2021). "The serum percentages of IL-9-producing CD4(+) T cells of the sepsis+IL-9 group were significantly higher than that of the sepsis group (3.53%±0.90% vs. 1.58%±0.41%, P =0.001) or the sepsis+sh-IL-9 group (3.53%±0.90% vs. 0.80%±0.02%, P < 0.001)." (PMID 33941281, 2021). "Compared with the sepsis group, the ZO-1 levels were significantly increased in the sepsis+sh-IL-9 group (P < 0.01), whereas those were significantly decreased in the sepsis+IL-9 group (P < 0.001)." (PMID 33941281, 2021). "We then measured plasma concentrations of IL-9 and IL-13 following sepsis, and demonstrated that both cytokines were markedly increased between 12 and 24 h after CLP." (PMID 29511181, 2018). "To characterize the type 2 cytokines secreted from lung ILC2 following sepsis, we measured IL-4, IL-9, and IL-13 expression in the ILC2 increased in the lungs by flow cytometry." (PMID 29511181, 2018). "Expansion of ILC2 in the lungs provides ILC2-derived IL-9 in the lungs, which reduces sepsis-induced EC pyroptosis through suppressing caspase-1 activation." (PMID 29511181, 2018). "In summary, this study obtained that increased IL-9 may aggravate intestinal injury in sepsis by affecting the occurrence of ferroptosis and thus exacerbating sepsis through clinical patient and animal model data." (PMID 41085701, 2026). "Besides the regular T helper lymphocytes, Th9 cells was found to be involved in the acute intestinal damage of sepsis through the IL-9 pathway in our previous study." (PMID 35042191, 2022). "Further studies are warranted to investigate whether IL-9 blockade has the potential to improve the mucosal barrier injury in sepsis." (PMID 33941281, 2021). "IL-9 blockade has the potential to improve the barrier injury in sepsis." (PMID 33941281, 2021). "IL-9 is closely related to intestinal mucosal barrier injury and mortality in sepsis." (PMID 33941281, 2021). "IL-9 also increased the mortality of sepsis in animal models." (PMID 33941281, 2021). "ILC2s can release IL-9 to prevent epithelial cell apoptosis in mice with sepsis." (PMID 34177881, 2021). "An increase in IL-9 acts to protect septic mice via a mechanism involving the modulation of proinflammatory and anti-inflammatory mediators, which may improve the survival rate in sepsis." (PMID 37175936, 2023).
Sepsis (continued). "Therefore, IL-9 and Th9 cells may be possible targets for the treatment of gastrointestinal dysfunction in early sepsis." (PMID 35042191, 2022). "However, whether IL-9-producing CD4(+) T cells and IL-9 have protective effects in sepsis need confirmation by more studies." (PMID 33941281, 2021). "Consequently, it is reasonable to speculate that Th9 and IL-9 may be related to the barrier injury in sepsis." (PMID 33941281, 2021). "Therefore, inhibition of Th9 cells differentiation or IL-9 expression may be a novel strategy to improve survival in sepsis." (PMID 33941281, 2021). "We hypothesized that IL-9 might mediate the ILC2-dependent MLEC protection in sepsis." (PMID 29511181, 2018). "This sepsis mouse model also showed increased presence of ILC2 in the lungs, where they secrete IL-9." (PMID 40568578, 2025). "However, it is unclear whether IL-9 is related to the intestinal barrier injury of sepsis." (PMID 33941281, 2021). "ILC2-derived IL-9, as shown in the data, through attenuating caspase-1 activation in MLEC reduces MLEC pyroptosis in sepsis." (PMID 29511181, 2018). "It is unclear whether IL-9-producing CD4(+) T cells and IL-9 are related to the acute injury of the intestinal mucosal barrier in sepsis." (PMID 33941281, 2021). "However, both Il-33−/− and Il1rl1−/− mice exhibited reduced levels of IL-9 and IL-13 in plasma and bronchoalveolar lavage fluid (BALF) after sepsis as compared with those in WT mice." (PMID 29511181, 2018). "Patients with sepsis had increased IL-9 levels compared to patients without sepsis." (PMID 33941281, 2021). "However, the roles of IL-9-producing CD4(+) T cells and IL-9 in sepsis are not clear." (PMID 33941281, 2021).
allergic rhinitis (11 papers, 2017 to 2022). Inflammation of the nasal mucous membranes caused by an IgE-mediated response to external allergens. "After using an IL-9 neutralizing antibody, the sneezing and nasal scratching times of allergic rhinitis mice were significantly reduced, and the OVA-IgE of peripheral blood was also reduced." (PMID 36172190, 2022). "The relative expression of these proteins was considerably lower than that in the allergic rhinitis group after using the IL-9 neutralizing antibody, and the difference was statistically significant." (PMID 36172190, 2022). "In previous experiments, we verified the therapeutic effect of IL-9 neutralizing antibody on a mouse model of allergic rhinitis which is described." (PMID 36172190, 2022). "After using an IL-9 neutralizing antibody, the relative expression of these proteins was significantly lower than in the allergic rhinitis group, and the difference was statistically significant." (PMID 36172190, 2022). "IL-9 is one of many cytokines that provide a new direction for the basic research of the pathogenesis of allergic rhinitis." (PMID 36172190, 2022). "After the intervention with the IL-9 neutralizing antibody, the symptoms of allergic rhinitis in mice were significantly reduced." (PMID 36172190, 2022). "IL-9 neutralizing antibody plays a therapeutic role in mice with allergic rhinitis, possibly through the TSLP-OX40/OX40L signal pathway and JAK1/2-STAT5 signal." (PMID 36172190, 2022). "IL-9 neutralizing antibody has a good therapeutic effect on the mouse model of allergic rhinitis, which may be related to the TSLP-OX40/OX40L pathway and JAK1/2-STAT5 signaling." (PMID 36172190, 2022). "Consequently, we used an IL-9 neutralizing antibody to counteract IL-9, and then observed and investigated the important role of IL-9 in the mouse model of allergic rhinitis." (PMID 36172190, 2022). "Therefore, IL-9 participated in the development and pathogenesis of allergic rhinitis." (PMID 36172190, 2022). "In the pathological section, IL-9 neutralizing antibody significantly inhibited the eosinophils infiltration and mast cells infiltration in the mouse nasal mucosa, which indicates the positive therapeutic effect of IL-9 neutralizing antibody on the mouse model of allergic rhinitis." (PMID 36172190, 2022). "In the co-seasonal ASIT regimen, only IL-9 (r=0.72-0.8, P<0.0001) and TNF-α (r=0.72-0.8, P=0.001 - P<0.0001) were significantly correlated with allergic rhinitis signs." (PMID 36439113, 2022). "After using an IL-9 neutralizing antibody, the mRNA expression of TSLP, TSLPR, OX40, OX40L, and IL-7R decreased significantly compared with the allergic rhinitis group, and the difference was statistically significant." (PMID 36172190, 2022). "The IL-9, PU.1, IRF4, and Th9 cell counts in AR patients are elevated in patients with allergic rhinitis compared with those in healthy controls." (PMID 36248862, 2022). "After using an IL-9 neutralizing antibody, the expression of JAK1/2 and STAT5 decreased significantly compared to the allergic rhinitis group, and the degree of phosphorylation also decreased significantly." (PMID 36172190, 2022). "After using an IL-9 neutralizing antibody, the mRNA expression of TSLP, TSLPR, OX40, OX40L, and IL-7R decreased significantly compared with the allergic rhinitis group." (PMID 36172190, 2022). "Nouri‐Aria et al25 studied the effects of 2 years of SCIT in grass pollen allergic rhinitis and showed that SCIT reduced numbers of mast cells and the mast cell growth factor IL9 protein and mRNA in the nasal mucosa." (PMID 32239697, 2020). "In conclusion, we infer that IL-9 neutralizing antibodies affect Th2 cells by neutralizing IL-9, thus affecting the secretion of cytokines and finally inhibiting eosinophil infiltration and OVA IgE secretion, which play a positive role in allergic rhinitis in mice." (PMID 36172190, 2022).
allergic rhinitis (continued). "Treatment with an anti-IL-9 antibody markedly reduces the number of Th2 cells in a mouse of allergic rhinitis, however, anti-IL-9 treatment does not affect ovalbumin-induced Th2 cytokine production by mice spleen T cells in vitro." (PMID 35524325, 2022). "ILC2, a type of innate lymphoid cells producing cytokines such as IL9, and IL13, plays an important role in eosinophilic asthma in response to respiratory infections, and is over-expressed in eczema lesions and in allergic rhinitis subjects." (PMID 28598986, 2017).
colorectal cancer (11 papers, 2019 to 2025). A primary or metastatic malignant neoplasm that affects the colon or rectum. "In colorectal cancer patients, Th9 cells and IL-9 promoted tumor growth, with both IL-9 and PU.1 elevated in intestinal mucosal tissues, and tumor growth inhibited in IL-9 or PU.1 knockout mouse models." (PMID 40909266, 2025). "Several studies have found that Prevotella and Bacteroides species have cross-talk with human colorectal cancer via interleukin-9." (PMID 39475915, 2024). "The finding of a correlation between Prevotella and the cytokines IL-5, IL-9 and IL-17A in the tumour microenvironment in colorectal cancer confirms a bidirectional interference between the host immune response and microbiota." (PMID 36407282, 2023). "Prevotella's lipopolysaccharides (LPS) have a proinflammatory effect and its abundance is negatively correlated with interleukin (IL)-17A in colorectal cancer samples while the correlation with IL-9 is positive." (PMID 35372388, 2022). "Significantly elevated levels of IL-4, IL-8 and IL-9 were observed in colorectal cancer." (PMID 37007080, 2023). "We next analysed the effect of an anti-IL-9 antibody on the development of colorectal cancer." (PMID 35793807, 2022). "To examine the potential relevance of IL-9 in patients with colorectal cancer, we addressed its expression in the presence or absence of tumour development." (PMID 35793807, 2022). "Since chronic inflammation is a potent driving force for the development of human colorectal cancer (CRC), the contributions of TH9/IL-9, TH17/IL-17, and TH22/IL-22 in the pathogenesis of CRC have recently become an increasingly popular area of scientific investigation." (PMID 31637216, 2019).